HGF (hepatocyte growth factor)
Diseases named in the same sentence as HGF in open-access papers (continued):
Sharing a sentence is not in itself a finding about the gene and the disease.
cancer (continued). "Furthermore, HGF influences the organization of the microtubules, which is essential to cancer cell motility, inversion, and EMT." (PMID 35630066, 2022). "The hepatocyte growth factor (HGF) is a growth factor that promotes cancer malignancy." (PMID 35085554, 2022). "Given the activities of activin and HGF in regulating CSC, we hypothesized that activin and HGF might have an important impact on CRC metastasis through the modulation of cancer stemness-related factors." (PMID 36591565, 2022). "The assay showed that the HGF treatment significantly induced cancer cell migration over the wound." (PMID 36139568, 2022). "One of the key hurdles in cancer therapy is overcoming drug resistance developed within heavily pre-treated refractory tumors and targeting the HGF/c-MET pathway could be a promising tool for addressing this." (PMID 36034555, 2022). "The overexpression of HAVcR-1 appeared to affect changes in the phosphorylation status of α and β-catenins, both of which are involved in cell motility and are part of the complex involved in HGF signalling, a key factor in the metastatic behaviour of cancer cells." (PMID 35204839, 2022). "In aggressive types of cancer where HGF and its receptors c-Met were highly expressed, anti-HGF nanobodies (1E2-Alb8 and 6E10-Alb8) labelled with positron emitter zirconium-89 was developed to be used for in vivo detection of HGF expression." (PMID 36071488, 2022). "Indeed, in some cases, the HGF/MET axis is crucial for cancer cell survival, and, in other cases, it has anti-cancer effects." (PMID 35986321, 2022). "Furthermore, transcriptional activation of HGF/c-MET signaling-related genes involved in cancer progression, invasion, metastasis, and cell survival were impaired." (PMID 35778602, 2022). "Particularly, tumour necrosis factor-α (TNF-α), interleukin-1β (IL-1β), and hepatocyte growth factor (HGF) have all been shown to cause mesothelial cell retraction, exposure of the underlying ECM, while facilitating the adhesion of cancer cells to the mesothelial cell monolayer." (PMID 36494669, 2022). "Mature HGF retained in the ECM is able to bind its receptor c-MET to mediate cancer progression." (PMID 36324128, 2022). "In addition, gene ontology analyses of the clinical GC cohort revealed significant correlation between IFITM3-associated genes and targets of c-MYC, which is a crucial downstream effector of HGF/MET pathway in cancer progression." (PMID 35941699, 2022). "Further experiments showed that sEV-HGF could activate the HGF/c-Met signaling pathway to promote cancer cell metastasis." (PMID 35158999, 2022). "TGF-β and HGF play key roles in several processes of cancer development." (PMID 34572947, 2021). "CAFs secrete hepatocyte growth factor (HGF) that mediates resistance to cancer cell apoptosis." (PMID 34503172, 2021). "HGF is known to be involved in migration of many cancer cell types, and a few reports have indicated that it may induce CCL20 secretion." (PMID 34853656, 2021). "HGF is a multi-functional and essential growth factor that, by binding to its receptor (c-Met), results in various effects, several of which are potentially related to growth and proliferation, invasion, and metastasis in cancer cells." (PMID 34930225, 2021). "Abnormal activation of the HGF/c-MET pathway and immune cell infiltration have been widely demonstrated to play an essential role in a variety of tumors, so we integrated HGF/c-MET pathway and immunoregulatory elements to analyze the underlying driving mechanisms of cancer." (PMID 34261467, 2021). "Therefore, HGF-MET signaling regulates cancer proliferation and invasion in the primary sites as well as subsequent growth in the metastatic lesions." (PMID 34436224, 2021). "Moreover, another pathogenic character of cancer is found in non-small cell lung cancer (NSCLC), that is, hepatocyte growth factor promotes cancer stem cell (CSC) sphere formation." (PMID 34209829, 2021).
cancer (continued). "HGF also induces cell proliferation, cancer cell motility and migration." (PMID 34503172, 2021). "Ferroptosis inhibitor (ferrostatin-1, Fer-1) restrained the B16F10 cancer-killing capacity of HGF remarkably, whereas the apoptosis inhibitor (carbobenzoxy-valyl-alanyl-aspartyl-[O-methyl]-fluoromethylketone, Z-VAD-FMK) and the necroptosis inhibitor (necrostatin-1s, Nec) did not." (PMID 34593794, 2021). "However, this signaling pathway can promote the development of Met-addicted tumors, indicating that the HGF/c-Met pathway plays a double-edged role in cancer." (PMID 34970484, 2021). "In addition to granular proteins, neutrophils also play a role in promoting cancer growth by releasing growth factors, including epidermal growth factor, hepatocyte growth factor (HGF) and platelet-derived growth factor." (PMID 34674757, 2021). "Hepatocyte growth factor (HGF) is a multifunctional growth factor which is secreted by mesenchymal stem cells that play crucial roles in accelerating the invasion and metastasis of several cancer cells." (PMID 34683124, 2021). "Moreover, PSC also promote EMT in cancer cells by secreting hepatocyte growth factor, and the hepatocyte growth factor also promotes the expression of cancer stem cell pluripotency markers in cancer cells." (PMID 34988078, 2021). "It is important to identify biological pathways that may contribute to these disparities, and due to its role in cancer progression and differences in its expression, HGF is a plausible contributor." (PMID 34344422, 2021). "Activation of PDGFRb, in particular on fibroblasts, has also been demonstrated to induce an upregulation of hepatocyte growth factor (HGF) and stanniocalcin-1 (STC1), with the latter having furthermore been linked to increased distant metastasis in several murine cancer models." (PMID 33661437, 2021). "HGF (hepatocyte growth factor) is known to promote invasion and migration in cancer." (PMID 34582708, 2021). "In this regard, the majority of currently available mouse systems might not be suitable to investigate the role of HGF/MET signaling in cancer treatment resistance mechanisms since mouse HGF has limited binding affinity to human MET." (PMID 34771620, 2021). "Moreover, enriched cellular iron contributed by our HGF strengthens the cancer cellular ferroptosis further." (PMID 34593794, 2021). "Based on these previous reports, we hypothesized that the HGF/c-Met pathway could contribute to the increase of Treg in cancer patients." (PMID 34771724, 2021). "After binding to MET, HGF mediates cell proliferation, cell motility as well as morphogenesis by stimulating a tyrosine kinase signaling cascade, and it is one of the growth factors responsible for triggering MMPs in cancers." (PMID 33500715, 2021). "In addition, hyperactive HGF/c-Met signaling also promotes the growth, survival, and metastasis of the cancer cells." (PMID 34804015, 2021). "At the initial stages of malignancy, fibroblasts could secrete TGFβ and hepatocyte growth factor to induce the initiation of cancer within the normal human epithelium." (PMID 34735373, 2021). "Aberrant HGF/c-Met signaling activation has been identified in multiple cancers." (PMID 34804015, 2021). "While HGF is associated with a poor prognosis particularly in patients with GC, the role of HGF in Treg accumulation in the context of cancer has not been documented." (PMID 34771724, 2021). "The HGF/cMET signaling axis contributes to tumorigenesis in various cancers." (PMID 33738970, 2021). "However, recent studies have found that the HGF/c-Met pathway plays a multifunctional role in regulating physiological and pathological processes, including cancer." (PMID 34970484, 2021). "Cancer cells with high c-Met expression are more sensitive and invasive to HGF." (PMID 34122599, 2021). "Typically, the hepatocyte growth factor (HGF) can activate cancer cell invasion and metastasis." (PMID 34660589, 2021).
cancer (continued). "As for another key factor of HGF/c-Met signaling, some investigators found that the high levels of circulating HGF might be an independent poor prognostic factor in patients with advanced cancers." (PMID 34804015, 2021). "c-Met activation in cancer can occur by gene mutation, amplification and overexpression independent of binding to its ligand hepatocyte growth factor (HGF)." (PMID 34795238, 2021). "HGF regulates the sugar metabolism pattern of cancer cells to induce the growth of cancer cells." (PMID 34683124, 2021). "In addition, today novel drugs targeting c-MET or HGF are being developed and tested in ongoing or completed clinical trials in other cancer-cell types." (PMID 35582373, 2021). "The HGF designed is heralded as an attractive candidate for next-generation cancer immunotherapy." (PMID 34593794, 2021). "HGF and its receptor c-Met plays an important role in cancer growth and metastasis." (PMID 34683124, 2021). "•Cabozantinib inhibits both GAS6-AXL and HGF-MET pathways in cancer cells." (PMID 32055714, 2020). "In addition, from a clinical point of view, cancer patients identified for HGF-based preventive cardioprotective therapy should be selected on the basis of a precise analysis of Met genetic lesions." (PMID 32722178, 2020). "Taken together, the role of HGF/MET in cancer seems to be quite complicated." (PMID 32435640, 2020). "Dysregulated HGF-c-Met activation is observed in a wide range of malignant tumors." (PMID 32626713, 2020). "In addition to metabolic reprogramming providing an energy source to foster cancer cells, TGF-β activated CAFs secrete growth factors, such as TGF-β, FGF2, FGF7, VEGF, PDGF, and HGF, to promote cancer cell proliferation." (PMID 33322749, 2020). "•Response to GAS6 and HGF for cell migration differs between cancer cell lines." (PMID 32055714, 2020). "•GAS6-AXL and HGF-MET pathways independently contribute to cancer cell migration." (PMID 32055714, 2020). "Aberrant HGF/c-Met signaling has been well known to play central roles in tumorigenesis and cancer progression with poor prognosis, suggesting that the c-Met/HGF axis may be considered as a promising therapeutic target." (PMID 32626713, 2020). "Overactivation of the c-MET/HGF system is a feature of many cancers." (PMID 33212946, 2020). "Interestingly, YAP interacts with HIF-1 upon HGF treatment and induces cancer stem cell pluripotency via increasing Nanog, OCT4, and SOX-2 expression." (PMID 32722184, 2020). "The HGF levels in cancer tissue are not simply associated with pMET because only tcHGF—but not scHGF, which exists at much higher levels than tcHGF—is a key molecule for the activation of MET." (PMID 33121208, 2020). "The crosstalk between lncRNAs and cricRNAs and HGF/c-Met axis in cancers." (PMID 32083078, 2020). "Moreover, overexpression of c-Met has been implicated in poor prognosis of patients with these forms of cancer, suggesting the possibility for HGF/c-Met axis as a potential therapeutic target." (PMID 33195182, 2020). "Among hundreds of thousands of signal receptors contributing to oncogenic activation, tumorigenesis, and metastasis, the hepatocyte growth factor (HGF) receptor – also called tyrosine kinase MET – is a promising target in cancer therapy as its axis is involved in several different cancer types." (PMID 32435640, 2020). "•Cabozantinib inhibits GAS6 and HGF combination-induced cancer cell invasion." (PMID 32055714, 2020). "However, dysregulated overactivation of pro-HGF has been reported to aggressively induce cancer invasion and metastasis through increased phosphorylation of MET." (PMID 32290402, 2020). "Thus, a continuous positive feed forward loop is established increasing the overall facilitatory effect of HGF on cancer progression." (PMID 33271944, 2020).
cancer (continued). "One possible explanation may be that by the time the treatments are instituted in vivo, the cancer cells have already disseminated and HGF/c-MET inhibition by itself cannot exert any evident anti-cancer effects." (PMID 32203220, 2020). "HiP-8 could selectively detect active HGF in cancer tissues, and active HGF probed by HiP-8 showed co-localization with activated MET." (PMID 33121208, 2020). "We found that while HGF or c-MET inhibition alone had variable effects on cancer migration, stemness and EMT, simultaneous inhibition of both the ligand and receptor (Hi + Ci) consistently reduced cancer cell migration/invasion into collagenous matrices, stem cell marker expression and EMT." (PMID 32203220, 2020). "The ability of low-dose curcumin to decrease the EMT phenotypes of cancer cells in conjunction with targeting HGF secretion by fibroblasts lends support for potential use in a long-term prevention or maintenance setting, particularly where low toxicity remains a priority." (PMID 31963196, 2020). "Inhibition of hepatocyte growth factor/c-Met could block cir-CCDC66-induced cancer stem cell enrichment." (PMID 31994979, 2020). "The crosstalk between microRNAs and HGF/c-Met axis in cancers." (PMID 32083078, 2020). "HGF is involved in cancer progression, and thus tumors driven by Met alterations (amplification and/or overexpression) could exploit HGF to develop and progress." (PMID 32722178, 2020). "Furthermore, recent research suggests that the HGF-c-Met axis limits the efficacy of cancer immunotherapy by modulating immune cell function and the expression of programmed cell death ligand 1 (PD-L1)." (PMID 32182714, 2020). "The HGF/MET pathway is considered a promising target in multiple cancer types." (PMID 32435640, 2020). "HGF is a fibroblast-derived growth factor found to stimulate the mobility of epithelial cells and was later shown to play an important role in the progression of malignant tumors." (PMID 33072555, 2020). "This chapter summarizes the interaction between the HGF/c-Met axis and ncRNAs in common cancers." (PMID 32083078, 2020). "Our previous studies have shown that cancer cell proliferation induced by human PSC secretions could be prevented by adding an HGF-neutralising antibody to the conditioned medium." (PMID 32203220, 2020). "With regard to the movement of cancer cells across the endothelial cell barrier during metastasis, HGF facilitates cancer cell–endothelial cell contact through phosphorylation of focal adhesion kinase (FAK) and reduces occludin, the primary protein in endothelial tight junctions." (PMID 33271944, 2020). "The production of TGFβ, leukaemia inhibitory factor (LIF), growth arrest-specific protein 6 (GAS6), fibroblast growth factor 5 (FGF5), growth differentiation factor 15 (GDF15) and hepatocyte growth factor (HGF) promotes invasive and proliferative behaviour in cancer cells." (PMID 31980749, 2020). "Besides α5β1 integrin, NRP1 co-interacts EGF with EGFR, and HGF with c-Met, and activates these pathways which participate in the proliferation of cancer cells." (PMID 32560565, 2020). "In addition, it is known that depletion of MACC1 also leads to disruption of the HGF/c-Met signaling pathway and sensitizes chemotherapy-resistant cancer cells." (PMID 33425885, 2020). "•Cabozantinib inhibits GAS6 and HGF combination-induced cancer cell migration." (PMID 32055714, 2020). "HGF/MET signaling-induced EMT is a major phenomenon in various cancer cells." (PMID 32290402, 2020). "It has also been shown that lactate (produced by MET/EGFR TKI-resistant cancer cells) enhances the production/secretion of HGF by cancer-associated fibroblasts, which in turn activates MET-dependent signalling pathways in cancer cells, causing adaptive resistance to MET inhibitors." (PMID 33271944, 2020). "Finally, we also examined the expression of anti-oxidant HO-1 in control and Nrf2 knocked down cancer cells after the sorafenib and HGF treatment." (PMID 30647407, 2019).
cancer (continued). "HGF concentrations can rise in patients with liver disease, myocardial infarction, and cancer." (PMID 30719213, 2019). "Moreover, we found that SRF deficient cardiomyocytes express higher levels of hepatocyte growth factor (HGF), which was attenuated by LIUS treatment in non-cancer cells." (PMID 31355136, 2019). "Moreover, activated fibroblasts present in the cancer cells niche secrete HGF, which is also described as mitogenic factor for melanocytes and can increase their invasion." (PMID 31649529, 2019). "Therefore, 3‐Cl‐AHPC is able to block matriptase/pro‐HGF/c‐Met cascade via down‐regulating matriptase activity to inhibit cancer cell scattering, migration and invasion." (PMID 30370662, 2019). "Therefore, high c-MET expression and involvement of HGF/c-MET pathway has been observed in a large part of cancer and has been correlated with poor patient survival." (PMID 30642077, 2019). "MET, the receptor of hepatocyte growth factor, was identified as a cancer stem cell marker in PDAC." (PMID 31311829, 2019). "Inhibition of c-MET signaling may impair cancer cell growth and at the same time stimulate immune responses via relieving HGF/c-MET induced immunosuppressive effects on mono-macrophages and on T cells." (PMID 30642077, 2019). "We also assayed the effects of these antibodies on HGF-induced cancer cell invasion." (PMID 30760737, 2019). "Moreover, gene amplification of c-Met is observed to couple with enhancement of K-Ras oncogene, and the Wnt/β-catenin functional interaction with HGF/c-Met pathways in cancer cells is identified." (PMID 30885237, 2019). "However, more frequently, MET signalling is activated by the hepatocyte growth factor/scatter factor, HGF, produced by adjacent mesenchymal tissues, including stromal components of cancers." (PMID 31296956, 2019). "c-MET, a high-affinity receptor for hepatocyte growth factor (HGF), is deregulated in many cancers." (PMID 30850583, 2019). "HGF/c-Met signalling pathway plays an important role in the development of cancers." (PMID 30422010, 2019). "YYB-101 is a humanized monoclonal antibody against HGF and a potential cancer treatment." (PMID 31355133, 2019). "However, the data from the Cancer Cell Line Encyclopedia (CCLE) database suggested that there were more hepatocyte growth factor (HGF) expression—the ligands of MET kinase—in SK-N-SH cells compared with the three other cell lines." (PMID 31137515, 2019). "Therefore, despite the proven clinical benefits of LP, multiple cancer cell phenotypes commonly escape its therapeutic effects through the activation of alternative survival pathways, including HGF/c-Met pathway." (PMID 30781364, 2019). "Indeed, if in some cases, HGF/MET is essential for cancer cell survival and it is one of the main drivers, in other cases it promotes anti-cancer effects." (PMID 30441809, 2018). "Therefore, finding effective c-MET inhibitors and understanding the regulation of HGF/c-MET pathway are crucial for further inhibiting prolonged activation of this pathway in human cancers, including digestive system cancers." (PMID 30360560, 2018). "Given the importance of HGF/Met signaling in these cell lines, and the fact that foretinib is a kinase inhibitor designed to target HGF/Met signaling, the powerful anti-cancer effects of foretinib on EC cells that were observed in the current study are not surprising." (PMID 29854314, 2018). "PDBu and HGF also function as potent stimulators of cell migration in cancer." (PMID 29986736, 2018). "Moreover, the MET/HGF axis is involved in the crosstalk between cancer cells and the surrounding microenvironment." (PMID 30544501, 2018). "The significance of the HGF/c-Met signalling in cancer has been extensively documented." (PMID 30314527, 2018). "Consequently, HGF/Met signaling has become an attractive therapeutic target in cancer and has been the focus of numerous research studies." (PMID 29854314, 2018).